NACA (nascent polypeptide associated complex subunit alpha)
Description:
Cardiac- and muscle-specific transcription factor. May act to regulate the expression of genes involved in the development of myotubes. Plays a critical role in ventricular cardiomyocyte expansion and regulates postnatal skeletal muscle growth and regeneration. Involved in the organized assembly of thick and thin filaments of myofibril sarcomeres (By similarity). Prevents inappropriate targeting of non-secretory polypeptides to the endoplasmic reticulum (ER). Binds to nascent polypeptide chains as they emerge from the ribosome and blocks their interaction with the signal recognition particle (SRP), which normally targets nascent secretory peptides to the ER. Also reduces the inherent affinity of ribosomes for protein translocation sites in the ER membrane (M sites). May act as a specific coactivator for JUN, binding to DNA and stabilizing the interaction of JUN homodimers with target gene promoters.
Synonyms: skNAC; NAC-alpha; HSD48; NACA1; Alpha-NAC
Tractability: Small molecule: a structure with a bound ligand is known. PROTAC: UniProt records ubiquitination sites on it; ubiquitination databases record sites on it; its protein half-life has been measured.
Gene: Protein-coding gene on chromosome 12 (56,712,305 to 56,731,628, reverse strand). Ensembl gene ENSG00000196531.
Subcellular location: Cytoplasm; Nucleus
Subcellular location (Human Protein Atlas): Cytosol
Pathways (Reactome):
Disease: Dengue Virus Genome Translation and Replication
Gene Ontology:
Biological process: protein targeting to membrane
Cellular component: cytoplasm; nascent polypeptide-associated complex; nucleus
Genetic constraint (gnomAD): Loss-of-function variants: 38 observed, 79.45 expected, observed/expected ratio (o/e) 0.48, 90% interval 0.37 to 0.63. The upper end of that interval is the gene's LOEUF score, 0.63, which puts it in group 2 of 6, group 1 being the genes least tolerant of losing a copy. Missense variants: 2,073 observed, 2,186.8 expected, observed/expected ratio (o/e) 0.95, 90% interval 0.91 to 0.98. Synonymous variants: 855 observed, 842.71 expected, observed/expected ratio (o/e) 1.01, 90% interval 0.96 to 1.07.
Homologues: Orthologues: macaque NACA (84% identical), mouse Naca (51% identical), rat Naca (48% identical), tropical clawed frog naca (21% identical), dog NACA (10% identical), zebrafish naca (10% identical), Caenorhabditis elegans icd-2 (6% identical). Paralogues in human: NACAD (13% identical), NACA2 (9% identical).
Diseases named in the same sentence as NACA in open-access papers:
NACA is named in the same sentence as 18 diseases in open-access papers, as found by Europe PMC text mining. Sharing a sentence is not in itself a finding about the gene and the disease. The quoted sentences say what the papers report.
Tetralogy of Fallot (2 papers, 2017 to 2022). A congenital cardiac malformation comprising pulmonary stenosis, overriding aorta, ventricular septum defect, and right ventricular hypertrophy. "Nacα specifically has been associated with Tetralogy of Fallot and increased myocardial mass." (PMID 36240221, 2022). "Our findings identify PEX5, NACA, ATXN2, CELA1, PCDHB4 and CTBP1 mutations as underlying genetic causes of isolated tetralogy of Fallot." (PMID 29291004, 2017). "Analysis using Gene Ontology /pathway, Online Mendelian Inheritance in Man, PubMed and other databases revealed that PEX5, NACA, ATXN2, CELA1, PCDHB4 and CTBP1 were associated with Tetralogy of Fallot." (PMID 29291004, 2017).
Alzheimer disease (1 paper, 2022). A progressive, neurodegenerative disease characterized by loss of function and death of nerve cells in several areas of the brain leading to loss of cognitive function such as memory and language. "Patients with Alzheimer’s disease and Down’s syndrome have lower NACA expression levels in their brain cells." (PMID 35620480, 2022).
asthma (1 paper, 2025). "The pathophysiological features of asthma were significantly attenuated by both NAC and AD4/NACA in vivo, as demonstrated in the ovalbumin (OVA)-induced murine model of asthma." (PMID 41129928, 2025).
cystinosis (1 paper, 2022). Cystinosis is a metabolic disease characterized by an accumulation of cystine inside the lysosomes, causing damage in different organs and tissues, particularly in the kidneys and eyes. "Therefore, further study of NACA and diNACA as potential treatments for cystinosis is warranted." (PMID 35710564, 2022).
dermatitis (1 paper, 2025). An inflammatory process affecting the skin. "Nascent-polypeptide-associated complex (NACA) binds to newly created polypeptides to prevent wrong translocation to the endoplasmatic reticulum and plays a role in bone formation and red blood cell differentiation and has been linked to dermatitis." (PMID 40957660, 2025).
retinitis pigmentosa (1 paper, 2022). Retinitis pigmentosa (RP) is an inherited retinal dystrophy leading to progressive loss of the photoreceptors and retinal pigment epithelium and resulting in blindness usually after several decades. "An oral dosage form of NACA is the subject of an ongoing clinical trial for the treatment of retinitis pigmentosa (Safety and Efficacy of NPI-001 Tablets for RP Associated with Usher Syndrome (SLO RP) (ClinicalTrials.gov Identifier: NCT04355689))." (PMID 35710564, 2022).
viral infection (1 paper, 2021). "AutoAgs such as LCP1 and NACA that are altered in the T cells of COVID patients may provide insight into T-cell responses in the viral infection and merit further study." (PMID 34729561, 2021).
cancer (7 papers, 2015 to 2025). A tumor composed of atypical neoplastic, often pleomorphic cells that invade other tissues. "Thus, the Nacα mutants in Drosophila not only advance our understanding of larval fat bodies, but also open new avenues for future research and strategies for cancer therapy." (PMID 37658058, 2023).
NACA also shares sentences with these, for which no sentence is quoted: chronic myeloid leukemia (1 paper); Down syndrome (1); hematologic disorder (1); infection (1); Infertility (1); lung (1); lung adenocarcinoma (1); neurodegenerative disease (1); tumor (1); Usher syndrome (1).